LEP (leptin)
Diseases named in the same sentence as LEP in open-access papers (continued):
Sharing a sentence is not in itself a finding about the gene and the disease.
Obesity (continued). "Atopic dermatitis (AD) and obesity have similar pathological manifestations, including inflammation as well as insulin and leptin resistance." (PMID 39564133, 2024). "The network of cardiometabolic proteins in obesity showed that the strongly higher-expressed LEP in the obese group interacts with the less-expressed GHRL and more-expressed GH1." (PMID 38732002, 2024). "Its serum concentration positively correlates with BF mass, and leptin resistance is another feature of obesity and type 2 diabetes." (PMID 38337640, 2024). "Here, we explore the correlation between leptin levels and diabetes or obesity through a meta-analysis." (PMID 39684379, 2024). "In obesity, leptin levels rise substantially as fat mass increases and in the context of leptin resistance, which limits its anorexigenic effects." (PMID 38642584, 2024). "This interaction promotes a decrease in leptin sensitivity, ultimately promoting obesity by reducing lipolysis." (PMID 39125332, 2024). "among the top 10 occurrences of keywords, we also found bariatric surgery, metabolic syndrome, insulin resistance, body mass index, and leptin, which are all keywords that are closely related to the topics of obesity and hypothyroidism." (PMID 38181287, 2024). "Leptin functions as a molecular connectionbetween obesity-induced oxidative stress andits complications such as insulin resistance, type 2diabetes, metabolic syndrome, liver fibrosis, and cardiovascular diseases." (PMID 39139165, 2024). "Fasting plasma adiponectin, corticosterone, ghrelin, and leptin were measured to assess the effect of H4CBD on levels of adipocytokines and other hormones associated with insulin resistance and obesity." (PMID 37899754, 2024). "Despite the theoretical anticipation that high leptin levels in obesity should lead to reduced food intake and increased energy expenditure, the “leptin resistance” phenomenon complicates this relationship." (PMID 38398459, 2024). "Our results confirmed that 13- and 26-week HFHS diets induced obesity in rats, characterized by dyslipidemia, impaired glucose regulation, intestinal dysbiosis, and altered leptin levels." (PMID 39765737, 2024). "This study demonstrates significant associations between dietary fat composition, inflammatory markers, and leptin levels in individuals with obesity." (PMID 39700087, 2024). "Among various factors, leptin, adiponectin, and several cytokines contribute to the inflammatory process of obesity and asthma and are regulated by or affect the function of immune cells." (PMID 38365763, 2024). "Energy-rich diets promote obesity by increasing adipose tissue weight, leptin and insulin resistance, disturbances in glucose metabolism, and the incidence of type 2 diabetes." (PMID 39201705, 2024). "Empirical evidence derived from obesity models indicates that, despite elevated leptin concentrations, the anticipated physiological responses are not achieved due to the underlying resistance mechanisms." (PMID 39594988, 2024). "The interaction of CART and leptin in obesity appears to be synergistic in the setting of reproductive dysfunction." (PMID 39595164, 2024). "Adipocyte hypertrophy and hyperplasia also alter the secretory profile of ASCs, resulting in excess production of cytokines and adipokines, including leptin, which promote inflammation in obesity." (PMID 39439572, 2024). "Poor sleep is also associated with high body mass index as sleep deprivation has been shown to increase the level of growth hormone-releasing peptide (Ghrelin) and reduced level of leptin thus increasing hunger and food intake promoting overweight and obesity." (PMID 40655880, 2024). "Leptin is an obesity-related hormone secreted by the adipose tissue and has been implicated as a link between obesity and breast cancer." (PMID 38791252, 2024).
Obesity (continued). "The persistence of leptin resistance in obesity and its impact on cognitive function, particularly within the hippocampus, highlights a critical intersection between metabolic and neurological health." (PMID 39594988, 2024). "Leptin resistance, characterized by diminished responsiveness to elevated leptin levels, disrupts hippocampal function and exacerbates both obesity and cognitive impairments." (PMID 39594988, 2024). "As BMI increases, obesity can also influence the HPT axis through factors such as leptin, lipotoxicity, and inflammatory adipokines." (PMID 39625889, 2024). "Administration of a probiotic bacterium, such as Lactobacillus rhamnosus GG (LGG) increases the sensitivity to exogenous leptin and reduced the proportion of Bacteriaidets/ Firmicutes and Proteobacteria in fecal microbiota in mice with dietary-induced obesity." (PMID 38807723, 2024). "Apart from the well-known obesity genes (LEP, PCSK1, NTRK2), we identified several BMI effector genes that have not been reported in GWAS but are supported by multiple converging lines of evidence." (PMID 38167462, 2024). "To confirm the influence of obesity on endothelial EPAS1 levels, we analyzed an alternative model of obesity using mice with homozygous deficiency in leptin (Lepob/ob), which gained weight more rapidly than littermate controls." (PMID 39234692, 2024). "Pro-Inflammatory cytokines and adipocytes, as leptin or chemerin, are known to be upregulated in obesity and to inhibit bone physiology." (PMID 39300501, 2024). "In obesity, disrupted leptin signaling compromises this process, leading to poor uterine vascularization and a suboptimal environment for embryo implantation." (PMID 39767708, 2024). "HFD-induced hyperleptinemia contribute to the burden of obesity and insulin resistance by impairing the leptin signaling." (PMID 38352704, 2024). "In this study, we observed obesity-related increases in leptin in both NGT-obese and GDM-obese participants." (PMID 38035802, 2024). "Since the identification of adiponectin and leptin as representative adipokines that regulate obesity, numerous types of adipokines have been discovered, prompting extensive research into their roles in health and metabolic diseases." (PMID 38672227, 2024). "Overweight/obesity was also linked to increased plasma levels of IL-5, IL-17A, IL-22, IL-33, TNF-α, and leptin and decreased levels of IL-10." (PMID 39902293, 2024). "These disruptions impede the effective transduction of leptin signals, thereby exacerbating the obesity phenotype." (PMID 39594988, 2024). "Obesity has been proved to induce increased levels of leptin, which affects anti‐tumor immunity by increasing PD‐1 expression and promoting T cell exhaustion." (PMID 38923758, 2024). "Clinical studies have elucidated the possible role of symbiotic supplementation on obesity biomarkers including Leptin." (PMID 38744950, 2024). "Three genes encode important components related to energy intake and energy expenditure balance such as Leptin (LEP), ghrelin (GHRL), melanocortin-4-receptor (MC4R), and the fat mass and obesity-associated gene (FTO)." (PMID 38863583, 2024). "Obesity induces the secretion of inflammatory factors, increases leptin plasmatic levels, dysregulates the clock genes from AT, and exacerbates insulin resistance in pregnant women." (PMID 39083072, 2024). "Studies on animals and humans have indicated that acupuncture reduces weight by regulating obesity-related neuropeptides (e.g., ghrelin, leptin, or serotonin) and reducing lipid levels." (PMID 38998814, 2024). "In individuals with obesity, the surplus energy, elevated leptin secretion, and down-regulation of leptin receptors lead to leptin resistance." (PMID 39625889, 2024). "A study showed participants with short sleep duration reduced leptin levels, increased auxin-releasing peptides, and heightened hunger and appetite, all of which can lead to obesity." (PMID 39839286, 2024).
Obesity (continued). "Recent studies have highlighted leptin, a key hormone that regulates energy intake and induces satiety, due to the worldwide prevalence of obesity." (PMID 39281006, 2024). "Our scRNA-seq analysis revealed that enrichment of the aging LEP gene expression signature in Luminal and Basal compartments was minimally affected by parity or obesity, reinforcing our findings in bulk tissue." (PMID 39545637, 2024). "Leptin levels in the white adipose tissue and plasma are related to the energy stores, such that leptin increases during a state of obesity and decreases during fasting." (PMID 39335493, 2024). "Prior research has demonstrated that Leptin, Protocatechuic Acid, and other molecules can combat obesity and atherosclerosis through MAPK3/ERK1." (PMID 38246999, 2024). "For example, in mice with diet-induced obesity, Withaferin A treatment significantly decreased plasma leptin concentrations but significantly restored leptin sensitivity, which in turn improved energy homeostasis and reduced bodyweight." (PMID 39064738, 2024). "Treatment with E2 has been shown to protect against obesity and alterations in glucose-insulin homeostasis in male mice fed high-fat diets, and to regulate leptin sensitivity to modulate feeding." (PMID 38883397, 2024). "MetS is a condition that favors leptin resistance through systemic inflammation, IR, hyperlipidemia, hypertension, atherosclerosis and obesity." (PMID 39728125, 2024). "Conversely, a recent multifaceted animal study highlighted the beneficial metabolic effects of reducing circulating leptin levels in mice with diet-induce obesity (DIO)." (PMID 38206766, 2024). "Significant research efforts have focused on the leptin signaling cascade to elucidate answers underpinning the hormonal resistance in obesity, however, this has led to underwhelming therapeutic traction." (PMID 39872508, 2024). "Restoring leptin sensitivity in obesity is a complex challenge, as leptin resistance often involves multiple pathways and factors." (PMID 39767708, 2024). "In adults with obesity, serum concentrations of IL-1RA have been shown to be significantly elevated and are influenced by factors such as serum leptin levels and lean body mass." (PMID 39201638, 2024). "Although the relationship between obesity and thyroid hormones is still not fully understood, it is believed that the increase in leptin levels secreted from the increased adipose tissue due to obesity stimulates thyroid functions." (PMID 38618433, 2024). "Whereas Cross-fit® + spinach-derived thylakoid decreased the proinflammatory leptin and resistin and increased the anti-inflammatory adiponectin and omentin in males with obesity, suggesting a reduction of inflammation, a feature of BF accumulation." (PMID 38337640, 2024). "Understanding these molecular pathways shows the relevance of the CART-leptin axis in obesity-related infertility and gives possible treatment targets to improve reproductive performance outcomes in obese women." (PMID 39595164, 2024). "Recent studies have described that accumulated BMAds contribute to circulating signal factors such as DPP4, RANKL and several well-known adipokines such as adiponectin and leptin in response to obesity, ageing or caloric restriction." (PMID 38704393, 2024). "Leptin levels are elevated and leptin resistance is observed in obesity, while adiponectin levels are diminished." (PMID 39339774, 2024). "Leptin, for instance, promotes osteoblast differentiation while inhibiting osteoclastogenesis; however, obesity-induced leptin resistance disrupts this regulatory balance." (PMID 39326787, 2024). "These and other data underscore how leptin functions as a bridge between inflammation and metabolism and can play a central role in the pro-inflammatory signaling that occurs in obesity and other metabolic disorders." (PMID 39439572, 2024).
Obesity (continued). "Recently, a gut–brain axis has been discovered that links the GIP effect on hypothalamic metabolic signaling to obesity-related leptin resistance." (PMID 39201336, 2024). "Understanding the pathogenesis of obesity-related disorders and the regulation of energy homeostasis by leptin should therefore provide new treatment options for obesity." (PMID 38541047, 2024). "Decreased adiponectin and increased leptin have been connected with insulin resistance in obesity, along with changes in other inflammatory cytokines." (PMID 39273478, 2024). "The modulation of leptin sensitivity in hypothalamic neurons plays a crucial role in metabolic regulation and the development of obesity." (PMID 39916981, 2024). "The experimental disease models included a broad range of conditions, such as diet-induced obesity and insulin resistance, NAFLD, leptin-deficient insulin resistance, and chronic vascular endothelial dysfunction." (PMID 39519561, 2024). "Serum leptin and adipocyte expression of the leptin gene (LEP or OB) are proportional to adipose tissue mass, with levels that generally rise with obesity and fall with weight loss." (PMID 38131197, 2024). "Our recent study, which combined the leptin resistance of the MSG model of early-onset obesity with FFC feeding, resulted in the development of strong steatosis with ballooning, increased collagen, and fibrosis." (PMID 39594513, 2024). "Ob/ob mice, an animal model of obesity, provided important information about the role of leptin in host defense and immunity, with nearly all innate immune cells being impaired in mice lacking intact leptin signaling." (PMID 38784180, 2024). "While leptin, often upregulated in obesity, has pro-tumorigenic effects by enhancing angiogenesis and cell proliferation, adiponectin, which is reduced in obesity, exhibits anti-inflammatory and anti-tumor properties." (PMID 39479267, 2024). "Numerous research findings have established a connection between leptin, its resistance, and diseases like DM and obesity." (PMID 38397015, 2024). "Although the placenta has also the ability to produce leptin, this increase appears to be solely due to the high adiposity observed in women with obesity." (PMID 39083072, 2024). "SBP showed positive correlations with obesity (BMI, % fat, fat mass, and serum leptin levels) and insulin resistance (insulin and HOMA-IR) factors, and a negative correlation with the insulin sensitivity parameter (QUICKI)." (PMID 39285220, 2024). "Leptin’s role in obesity and metabolic syndrome in women with PCOS is well-described, and one study also found elevated leptin levels in children with CAH." (PMID 39175574, 2024). "SHS exposure has been shown to alter hormone levels, such as leptin and insulin, which regulate appetite and energy balance, thereby promoting weight gain and obesity in children." (PMID 39457215, 2024). "Studies have shown that prebiotics can restore leptin sensitivity in rodents with HFD-induced obesity and diabetes, suggesting that targeting the gut microbiota can potentially restore adipokine homeostasis." (PMID 39335642, 2024). "Leptin, a cytokine crucial for regulating energy expenditure in adipocytes, is significantly elevated in individuals with obesity and chronic inflammation." (PMID 39065712, 2024). "Obesity regulates the levels of adipokines such as adiponectin and leptin, and 17β-estradiol regulates the levels of adiponectin and leptin in adipocytes and adipose tissue." (PMID 39273478, 2024). "Chronic hyperleptinemia in HFpEF patients is largely attributable to higher BMI, as obesity is both a driver of HFpEF pathogenesis and a key factor in increased leptin production." (PMID 39682585, 2024). "Leptin is present in the follicular fluid and its concentrations align with the serum concentrations, reaching higher levels in women with obesity." (PMID 39273337, 2024). "It involved 112 adults with obesity, each with at least one minor allele in the FTO, LEP, LEPR, or MC4R polymorphism." (PMID 38398881, 2024).
Obesity (continued). "Chronic IP application of TRH to DIO mice reduced food intake and body weight, and improved metabolic parameters related to obesity, such as decreased levels of leptin, triglycerides, or cholesterol." (PMID 38577975, 2024). "With the exception of adiponectin, obesity-related biomarkers including glucose, insulin, triglycerides, cholesterol, and leptin were significantly aggravated in human APOE expressing mice compared to unmodified C57BL/6J mice." (PMID 37450924, 2024). "This hypothalamic leptin resistance limits the direct therapeutic application of leptin for obesity." (PMID 39606796, 2024). "Obesity can lead to significant alterations in the levels of adipokines, such as adiponectin and leptin." (PMID 39700175, 2024). "Individuals with obesity and T2D present leptin resistance and higher circulating levels that drastically reduce the signaling of leptin in POMC neurons and the anorexigenic activity in the ARC." (PMID 39728000, 2024). "Previous research on the molecular link between obesity and BC has primarily focused on adipocyte dysfunction, the release of adipokines such as leptin, and hormonal changes involving insulin and peripheral estrogen aromatization in adipose tissues." (PMID 38402239, 2024). "Recent research has revealed a connection between obesity and thyroid autoimmunity, with the hormone leptin produced by adipose tissue as the primary link." (PMID 38526760, 2024). "Leptin levels are positively correlated with fat mass, resulting in elevated levels in individuals with obesity." (PMID 39444577, 2024). "This study not only uncovers a new role of SEL1L-HRD1 ERAD in the pathogenesis of diet-induced obesity and central leptin resistance, but a new regulatory mechanism for leptin signaling." (PMID 38260335, 2024). "On the other hand, PA, the primary saturated fatty acid in the Western diet and a significant contributor to human obesity, induces leptin resistance through mechanisms involving ER stress and inflammation." (PMID 39916981, 2024). "In peripheral tissues, such as the liver, decreased expression of hepatic LepRb has been observed in obesity, indicative of leptin resistance." (PMID 38623207, 2024). "Apart from the severe genetic disruptions of the leptin pathway that led to its discovery, we know surprisingly little 30 years later about the role of leptin action and resistance in human obesity." (PMID 38165042, 2024). "This study demonstrated that leptin/obR signaling (obR is the leptin receptor), plays an important role in the pathogenesis of obesity-related neutrophilic airway inflammation in females, by promoting M1 macrophage polarization." (PMID 38629073, 2024). "During obesity, leptin expression is increased, which shortens the G1 phase by promoting the transcription of cyclin D1, the regulator of the transition from the G1 to S phase." (PMID 39596205, 2024). "It is well known that obesity is characterized by an increased level of some adipokines such as leptin, resistin, visfatin, and a reduction of adiponectin." (PMID 38145995, 2024). "Anti-inflammatory diets, such as the Mediterranean diet, enhance leptin sensitivity and decrease leptin levels, while diets high in saturated fatty acids (SFAs) can induce leptin resistance, potentially leading to obesity." (PMID 38892561, 2024). "A prolonged obesity status is responsible for a leptin-mediated shift of CD8+ T cell metabolism from glycolysis to fatty acid oxidation." (PMID 38892411, 2024). "Leptin is involved in regulating food intake, energy expenditure, and glucose and fat metabolism as a potential biological link in the development of obesity." (PMID 39771044, 2024). "As in individuals with obesity, the levels of adiponectin, insulin, ghrelin, and leptin are disrupted, and the same molecules affect the regulation of the hypothalamic–pituitary–gonadal axis (HPG), impacting the timing of puberty." (PMID 39203868, 2024).